IL31 (interleukin 31)
Diseases named in the same sentence as IL31 in open-access papers (continued):
Sharing a sentence is not in itself a finding about the gene and the disease.
syringomyelia (1 paper, 2023). Syringomyelia is characterized by cerebrospinal fluid (CSF)-filled cavities (syrinx) inside the spinal cord, either as a result of a known cause (secondary syringomyelia, SS) or, more rarely, due to an unknown cause (primary syringomyelia, PS). "We hypothesized that dogs with syringomyelia and associated sings of pain or increased itching behaviour have higher levels of IL-31 in CSF and/or serum." (PMID 37993920, 2023). "As pain and dysesthesia are other clinical signs of dogs with syringomyelia and pruritus and pain share the same central pathways, we also examined the correlation between pain and IL-31 levels in serum." (PMID 37993920, 2023). "In 25 dogs IL-31 levels in paired serum and CSF samples were available: 18 dogs with syringomyelia (group A) and seven dogs from the healthy control group (group C)." (PMID 37993920, 2023). "Mean CSF IL-31 value was 146.3 pg/ml (n = 27) in dogs with syringomyelia and 186.2 pg/ml (n = 8) in healthy dogs." (PMID 37993920, 2023). "The purpose of this study was to investigate the correlation between IL-31 levels in serum and CSF in patients with syringomyelia and itching behaviour." (PMID 37993920, 2023). "This study investigates suspected elevated levels of IL-31 in serum and CSF of dogs showing signs of pain or increased itching behaviour related to syringomyelia." (PMID 37993920, 2023). "Of the dogs with syringomyelia and concomitant neurological disease (group C) only dogs with intervertebral disc herniation (n = 3/11) had IL-31 levels in serum above the healthy control group." (PMID 37993920, 2023). "An elevated IL-31 level > 1050 pg/ml was measured in the serum of one patient from group A.3 with syringomyelia and intervertebral disc extrusion." (PMID 37993920, 2023). "In summary, itching behaviour or signs of pain in dogs with syringomyelia seem not to be caused by increased IL-31 levels in serum and CSF." (PMID 37993920, 2023). "Since IL-31RA occurs in the dorsal horn of the spinal cord, we hypothesize that dogs with syringomyelia and signs of pain or itching behaviour have an elevated level of IL-31 in CSF and/or serum." (PMID 37993920, 2023). "Based on this study, increased IL-31 levels seem not to be correlated with itching behaviour or signs of pain in dogs with syringomyelia, but might be caused by other underlying diseases." (PMID 37993920, 2023). "In this retrospective, multicentre study, we included dogs with magnetic resonance imaging (MRI) confirmed syringomyelia with or without neurological comorbidities and examined serum and CSF IL-31 levels." (PMID 37993920, 2023). "Overall, the mean IL-31 level in patients with syringomyelia, and signs of pain was nearly about twice as high as the mean IL-31 value in the serum of patients with syringomyelia without pain, but the difference was not statistically significant (p = .1061)." (PMID 37993920, 2023). "Itching behaviour was not significantly correlated with increased IL-31 levels in serum of dogs with syringomyelia." (PMID 37993920, 2023). "Although IL-31 receptors are found in the dorsal horn of the spinal cord, we could not show an involvement of IL-31 in the pathogenesis of pain in syringomyelia." (PMID 37993920, 2023).
systemic mastocytosis (1 paper, 2025). Systemic mastocytosis (SM) comprises a heterogeneous group of rare acquired and chronic hematological malignancies that are related to an abnormal proliferation of mast cells in tissue, including bone marrow, with or without skin involvement. "Indeed, additional germline variants in KIT and in genes encoding for cytokines or their receptors (e.g., IL13, IL6, IL6R, IL31, IL4R), as well as increased copy numbers of the TPSAB1 gene encoding for α‐tryptase, have been increasingly recognized as associated with systemic mastocytosis in adults." (PMID 41177946, 2025).
thyroid autoimmunity (1 paper, 2023). "IL‐31 levels were higher in CSU patients with thyroid autoimmunity (assessed by anti‐TPO and/or anti‐TG) than in patients without thyroid autoimmunity, but the difference was not statistically significant." (PMID 37632245, 2023).
tuberculosis (1 paper, 2016). A chronic, recurrent infection caused by the bacterium Mycobacterium tuberculosis. "The combination of the pleural fluid IL-31 levels with the plasma tuberculosis-specific IL-31 levels constitutes a highly sensitive and specific assay for the differential diagnosis of TPE and MPE." (PMID 26864868, 2016). "Ultimately, the combination of pleural fluid with the plasma tuberculosis-specific IL-31 levels improved the sensitivity and specificity to 94.0% and 95.1%, respectively." (PMID 26864868, 2016). "Nevertheless, the role of IL-31 in tuberculosis is rarely studied." (PMID 26864868, 2016). "Furthermore, the tuberculosis-specific IL-31 levels in the plasma of TPE patients were higher than that of MPE patients (P = 0.0002)." (PMID 26864868, 2016).
tuberculous pleurisy (1 paper, 2016). "Because both the IL-31 levels in the pleural fluid and M.tb specific whole blood IL-31 release assay were highly sensitive and specific for the diagnosis of tuberculous pleurisy, we sought to combine these assays to improve the diagnostic power of IL-31 measurement for clinical use." (PMID 26864868, 2016). "Furthermore, the combination of the IL-31 levels in the pleural fluid and the M.tb specific whole blood IL-31 release assay was highly specific for the diagnosis of tuberculous pleurisy." (PMID 26864868, 2016). "The results showed that IL-31 is a highly sensitive and specific biomarker for the diagnosis of tuberculous pleurisy and could readily differentiate it from malignant pleural effusion." (PMID 26864868, 2016). "Therefore, the IL-31 levels in the pleural fluid and the M.tb specific IL-31 in the whole blood constitute a useful biomarker set for the diagnosis of tuberculous pleurisy." (PMID 26864868, 2016).
ulcers (1 paper, 2023). "In this study, the intradermal administration of IL-31 was shown to elicit statistically significant pruritic behaviors in healthy dogs over 5 h compared to the vehicle control group without causing apparent severe cutaneous self-injury (e.g., erosions/ulcers)." (PMID 37235412, 2023).
tumor (37 papers, 2013 to 2025). "The IL-6, IL-31, and IL-1RA predictions were primarily associated with tumor extent and smoking history, whereas the soluble receptors (s)-IL-6Rα, s-gp130, and s-IL-33Ra predicted survival even after such adjustments." (PMID 38672565, 2024). "Specifically, cytotoxic T cell activity is increased, whereas the levels of CD4+ T cells, MDSCs, and tumor-associated macrophages are decreased in IL-31-expressing tumors." (PMID 32843492, 2020). "Then, multivariate analysis using Cox proportional hazard models, adjusted by FIGO stage, histology type, and tumor grade, was carried out to examine the effects of IL-31 polymorphisms on patients' outcomes." (PMID 29484036, 2018). "IL-11 belongs to IL-6 cytokine family, which consisted of IL-6, IL-11, IL-27, IL-30, IL-31, oncostatin M, and others, and it can be secreted by cancer-associated fibroblasts, myeloid cells, and tumor cell itself." (PMID 25929737, 2015). "Collectively, while the antiangiogenic activity of IL31 has been demonstrated in vitro and in vivo, it remains to evaluate whether IL31 affects also subsets of endothelial cells, e.g., tumor associated endothelium, therefore explaining its potent antiangiogenic activity in vivo." (PMID 28147314, 2017). "In endometrial cancer, elevated IL-31 and IL-33 levels correlate with tumor stage, serving as prognostic biomarkers, while IL-11 blockade reduces tumor growth and metastasis in mouse models." (PMID 41029427, 2025). "IL‐31 and thymic stromal lymphopoietin, which are possibly secreted by tumor cells and infiltrating immune cells, are reported to be involved in itch in Hodgkin lymphoma." (PMID 39663861, 2025). "Pro-inflammatory cytokines such as IL-6, IL-8, IL-31, and IL-33 promote tumor growth and resistance to apoptosis." (PMID 38464838, 2024). "Notable decreased cytokines in the KEAP1-KO clones included IL-7R alpha, IL-18, IL-23, IL-31, and IL-33, which are pro-inflammatory and correlate with infiltration and activation of T cells and anti-tumor responses." (PMID 38542481, 2024). "IL-4 and IL-31 mediate the activation of eosinophils and mast cells and indirectly activate B lymphocytes to produce IgE, contributing to skin itching and allergic inflammation." (PMID 35805534, 2022). "Serum IL-31 was related to tumour stages (p = 0.024), and serum IL-33 was related to tumour stages (p = 0.035), depth of invasion (p = 0.008), nodal metastases (p = 0.029) and distant metastases (p = 0.036)." (PMID 34951691, 2022). "In recent years, studies on IL-31 in oncology have also focused on the variability of expression of the IL-31 gene, the identification of SNPs, and the correlation with clinical characteristics and tumor stages." (PMID 35742951, 2022). "Previous studies have suggested the involvement of IL-31 in itching diseases including atopic dermatitis (AD), other pathological conditions, drug-induced itch, and neoplastic diseases, such as CTCL." (PMID 34335777, 2021). "Circulating IL-31 was directly connected with the severity of itch in a neoplastic disease such as CTCL." (PMID 34118946, 2021). "More importantly, the pathological role of IL-31/IL31RA axis in tumor progression is largely unclear." (PMID 32528891, 2020). "We have shown that IL-31 affects the activation and M1/M2 polarization of macrophages from spleens of non-tumor-bearing mice infused with IL-31 as well as from PyMT-IL-31 tumors." (PMID 32843492, 2020). "Tumor cells produce IL-31, and IL-31 and its receptor are confirmed to affect the tumor microenvironment." (PMID 32513106, 2020). "Treating tumor-bearing mice with IL-31-L-IgG achieved a superior therapeutic effect in comparison with purified IL-31 delivered with osmotic pumps." (PMID 32843492, 2020). "To characterize the immunomodulatory role of IL-31, we first analyzed the changes in various immune cell populations on IL-31 infusion in tumor-free mice." (PMID 32843492, 2020).
tumor (continued). "Here we describe, for the first time, the immunological mechanisms by which IL-31 inhibits tumor growth." (PMID 32843492, 2020). "In vivo, the number of metastatic lesions in the lungs of 4T1 tumor-bearing mice is reduced when the mice are infused with IL31, in agreement with our in vitro findings." (PMID 28147314, 2017). "Next, we assessed the changes in tumor growth in mice administered with recombinant murine IL31 (rmIL31)." (PMID 28147314, 2017). "In contrast, MC38 tumor-bearing mice infused with recombinant IL31, exhibit a significant reduction in tumor growth than control mice." (PMID 28147314, 2017). "A significant inhibition of tumor growth was found in IL31-IgG-treated mice compared to control IgG-treated mice." (PMID 28147314, 2017). "Collectively, our findings demonstrate that IL31 inhibits endothelial cell activity both directly and indirectly probably through antiangiogenic mediators secreted by tumor cells." (PMID 28147314, 2017). "In this study we show that injecting tumor-bearing, chemotherapy-treated mice with IL31-IgG reduces tumor growth, angiogenesis and pulmonary metastases to a greater extent than when chemotherapy is used alone." (PMID 28147314, 2017). "Here we demonstrate that tumors from mice infused with IL31 exhibit reduced angiogenesis when compared to control untreated mice in both syngeneic murine tumors and human tumor xenografts implanted in NOD-SCID mice." (PMID 28147314, 2017). "Overall these results indicate that certain tumor types highly express IL31 and/or IL31RA, and thus suggest a potential role for the IL31-IL31RA axis in cancer." (PMID 28147314, 2017). "Lastly, injecting tumor-bearing, chemotherapy-treated mice with a long-lived IL31-IgG fusion protein reduces tumor growth, angiogenesis and pulmonary metastasis to a greater extent than when chemotherapy is used alone." (PMID 28147314, 2017). "The IL31 anti-tumor activity is explained, in part, by the anti-angiogenic effects demonstrated both in vitro and in vivo highlighting the potential use of IL31 as an anti-cancer drug." (PMID 28147314, 2017). "Collectively, these results suggest that continuous infusion of IL31 inhibits tumor growth, partly by an anti-angiogenic activity." (PMID 28147314, 2017). "These anti-metastatic effects can be explained by the anti-angiogenic effects of IL31 and by the decreased invasion and migration properties of tumor cells in the presence of IL31." (PMID 28147314, 2017). "Mice infused with IL31 exhibited tumor growth retardation and reduced number of pulmonary metastatic lesions." (PMID 28147314, 2017). "When tumors reached 100 mm3, mice were intraperitoneally injected with IL31-IgG twice weekly, and tumor growth was assessed over time." (PMID 28147314, 2017). "In tumor patients, IL-31 often produced by damaged and inflamed tissues, especially human mast cell, can also join the T helper type 2 (Th2) responses." (PMID 27340318, 2016). "Another logistic analysis of multitarget diagnostic value evaluation verified that the sensitivity and specificity combination of IL-31 and IL-33 were also higher than the counterparts of tumor markers." (PMID 27340318, 2016). "In this study, the serum levels of IL-31 and IL-33 in EC patients were studied and assessed the interrelationship with clinical significance and some tumor markers." (PMID 27340318, 2016). "It revealed that serum IL-31 was related to tumor stages (P = 0.024) and serum IL-33 was close to the disease process: tumor stages (P = 0.035), depth of invasion (P = 0.008), and existence of node metastases (P = 0.029) and distant metastases (P = 0.036)." (PMID 27340318, 2016). "IL-31, a pro-inflammatory cytokine, is involved in tissue remodeling and may indirectly support tumor progression by enhancing eosinophil-mediated inflammation." (PMID 40305195, 2025). "Some substances from tumor cells such as IL‐31, paraneoplastic neuropathy, and cancer treatments including radiotherapy may cause itching." (PMID 39663861, 2025).
tumor (continued). "Multiplex bead-based ELISA (Luminex) analysis of cell culture supernatant from 4T1 Vector, 4T1 MerTK C8, and 4T1 MerTK C11 tumor cells revealed significantly increased release of the pro-inflammatory cytokines IL-1 alpha and IL-31, and chemokines MCP-1 (CCL2) and MCP-3 (CCL7)." (PMID 40391157, 2025). "The precise role of IL-31 in tumor biology and treatment response remains uncertain." (PMID 40305195, 2025). "In a previous study, we observed that irradiating OAC tumour biopsy explants ex vivo had favourable effects on the secretome, significantly increasing the secretion of anti-tumour cytokines IL-21 and IL-31 and decreasing the production of a tumour-promoting cytokine IL-23." (PMID 38672174, 2024). "IL-31 is the only exception to the ‘gp130 rule’ of IL-6 subfamily for its receptor consisting of IL-31 receptor α and oncostatin receptor β, through which IL-31 joins the immune responses and tumor progression." (PMID 36531027, 2022). "All these findings suggest that SNPs of IL-31 could have a role in the diagnosis or prognosis of several epithelium-derived solid tumors, especially when in combination with other tumor-related markers." (PMID 35742951, 2022). "Additionally, two other regulatory cytokines, IL-35 and IL-31, induced by T. muris infection are able to modulate tumour immunity." (PMID 34078488, 2021). "As this cytokine has also been implicated in cancer progression, it is likely that T. muris induced IL-31 production may also enhance tumour progression in a manner similar to IL-35." (PMID 34078488, 2021). "It has been reported that IL-31 can improve angiogenesis and promote tumor progression." (PMID 34307161, 2021). "Likewise, we found that there was a correlation between IL-31Ra expression and modulation of immune cell subset, suggesting that IL-31 affects tumor immunity." (PMID 32843492, 2020). "Furthermore, gp130, IL6Rα, and IL31 were suggested to predict prognosis among tumor HPV-negative patients." (PMID 33066437, 2020). "High circulating plasma and tumor levels of IL-31 were confirmed in both models, and in the PyMT model a significant inverse correlation was found between IL-31 plasma levels and tumor size." (PMID 32843492, 2020). "Both IL-31-L-IgG and purified IL-31 inhibited tumor growth in comparison with controls." (PMID 32843492, 2020). "To this end, we isolated CD8+ cells from the spleens of non-tumor-bearing C57bl/6 mice, reaching purity of over 95%, and assessed whether IL-31 affects their activation or proliferation in vitro." (PMID 32843492, 2020). "Thus, IL-31 directly modulates macrophage activity and protein secretion toward a proinflammatory state, which can explain the antitumorigenic phenotype in the tumor." (PMID 32843492, 2020). "Intriguingly, the pathological roles of IL-31/IL31RA signaling in tumor progression remain largely unknown." (PMID 32528891, 2020). "We reported that IL-31 plasma levels inversely correlated with tumor size." (PMID 32843492, 2020). "Recent studies suggest that IL-31 may also contribute to hematopoietic malignancies and tumor growth in human lymphoma." (PMID 29484036, 2018). "The increase in the expression of IL-31 may be able to reverse cancer invasive and migratory abilities and inhibit tumor growth." (PMID 29484036, 2018). "In vivo, IL31-depleted MC38 tumor cells implanted to mice grow faster than control tumors." (PMID 28147314, 2017). "Therefore, it is plausible that IL31 inhibits endothelial cells indirectly by inducing the secretion of antiangiogenic mediators from human tumor cells." (PMID 28147314, 2017). "Comparing sensitivity and specificity of some tumor markers, we suppose that elevated serum IL-33 and IL-31 levels, especially IL-33, may relate to the process of EC and could be useful biomarkers for the diagnosis of that disease." (PMID 27340318, 2016).